CCND1 (cyclin D1)
Diseases named in the same sentence as CCND1 in open-access papers (continued):
Sharing a sentence is not in itself a finding about the gene and the disease.
tumor (continued). "In addition, studies have reported that cyclin D1, cyclin E, MMP-2 and MMP-9 are associated with tumor growth and metastasis inhibition in an A549 cell and its xenograft mouse tumor model." (PMID 29522490, 2018). "Altered ubiquitin-proteasome system is responsible for cyclin D1 overexpression in tumor cells." (PMID 30428594, 2018). "Analysis of Cyclin D1 protein expression showed significantly higher expression (p = 0.0095) in the samples with the deletion in comparison to analyzed tumours without CTNNB1 mutation." (PMID 29872083, 2018). "It is reported that concomitant over-expression of D1 type cyclin and under-expression of tumor suppressor p21 are pre-requisite for tumor initiation, as it is evidenced that down-regulation of cyclin D1 and over-expression of p21 in xenograft model abrogate the formation of primary tumor." (PMID 30108509, 2018). "High expression of CCND1 (cyclin D1) also correlates with tumor onset and tumor progression." (PMID 30380668, 2018). "Moreover, CXCL8 stimulation of PCa cells was described to regulate cyclin D1 expression, supporting cell cycle progression and PCa tumor growth." (PMID 29808619, 2018). "The most frequently mutated genes across all tumor types included KRAS (30 patients), PIK3CA (16 patients), BRAF (6 patients), EGFR (5 patients), NRAS (4 patients) and ERBB2 (3 patients) whereas CCND1, ERBB2, EGFR and MYC were the genes most frequently subjected to copy number gain." (PMID 29854313, 2018). "Herein, depletion of SLC7A11-AS1 had an effect on c-Jun and cyclin D1 overexpression that was related to tumor cell cycle progression, indicating that SLC7A11-AS1 regulated cell cycle and proliferation cause to SLC7A11 up-regulation by the c-Jun N-terminal kinase (JNK) and p38 pathways." (PMID 29348845, 2017). "A cyclin D1 sphere-derived xenograft tumor model was used to evaluate whether the induction of differentiation may serve as a strategy to target CSCs in vivo." (PMID 28415588, 2017). "Moreover, LY294002 and knockdown of Cyclin D1 or MMP9 remarkably blocked the tumor-promoting activity of NCOA5." (PMID 29296214, 2017). "Despite this, in our study, cyclin D1 and p21 immunohistochemical expression in pretreatment biopsies have prediction value and are two of the four variables that contribute for the statistical model capable to predict Mandard tumor response." (PMID 28938543, 2017). "Thus, pretreatment with a Smad inhibitor followed by chemotherapy not only successfully suppressed tumor growth but also eliminated 57% of the tumors in a cyclin D1 sphere-derived xenograft model." (PMID 28415588, 2017). "As cyclin D1 has been shown to promote cellular migration it will be of interest in future studies to determine whether stromal cyclin D1 correlates with increased tumor invasiveness." (PMID 29137220, 2017). "Furthermore, CAL27 mouse xenograft model confirmed that down-regulation of CREPT prohibited cyclin D1 and c-Myc expression, through which decreased the in vivo tumor growth, but increased the survival ratio of hosts." (PMID 28369091, 2017).
tumor (continued). "Consist with the results obtained from the in vitro study, immune-histochemical analyses demonstrated that the expression levels of EZH2, H3K27me3, MMP2, Vimentin, N-cadherin, ki-67 and Cyclin D1 were downregulated in tumor specimens from the GSK343-treated group." (PMID 29228694, 2017). "The highly correlated expression between IL-20 and cyclin D1 also suggests that IL-20 might be a predictive marker of HCC tumor growth." (PMID 29242565, 2017). "In addition, immunoblot analysis showed that reduction of BEX2 led to decreased expression of OPN and cyclin D1, and an increase in the level of cleaved-caspase 3 in tumor tissues derived from MHCC97H cells." (PMID 29029472, 2017). "The expression of cyclin D1 in isolated tumor sections was evaluated by immunohistochemistry." (PMID 28264020, 2017). "Indeed, we found that expression of NR4A1 in MDA-MB-231 cells inhibited JNK1 expression, c-Jun activation and cyclin D1 expression, which is correlated with the decreased cell proliferation and tumor growth of these cells." (PMID 28903348, 2017). "In addition, the CCND1 expression levels were higher in tumor tissues than in normal tissues, including the human bladder, breast, cervix, bile duct, colorectal, esophagus, head and neck, kidney, pancreas, stomach and uterus." (PMID 29199958, 2017). "By these targets, Trop2 could maintaining tight junction integrity 5; increases tumor proliferation through activated the NF‐kB, cyclin D1 and ERK; and suppresses IGF‐1R signaling." (PMID 28256068, 2017). "In contrast, SHP2 tyrosine phosphatase converts parafibromin from a tumor suppressor to an oncogenic driver by its interaction with and subsequent stablization of β-catenin to upregulate expression of Wnt target genes, including cyclin D1 and c-myc." (PMID 29221126, 2017). "Cyclin D1 is also reported to be involved in the regulation of tumor metastasis." (PMID 28602785, 2017). "Our data, therefore, strongly suggest that tumour cells proliferation may be controlled by nuclear cyclin D1, whereas tumour cells invasiveness may be controlled by the cytoplasmic fraction of the protein." (PMID 29066743, 2017). "In conclusion, despite the partly discordant results of the large transATAC study, most previous analyses of the impact of cyclin D1 expression in ER-positive breast cancer have, like the present one, shown high expression to be a sign of tumor aggressiveness and poor prognosis." (PMID 28528450, 2017). "The tumor expression levels of cyclin D1 and c-Myc, which are major target genes of the Wnt/β-catenin signaling pathway, were comparable between the DEN-treated LIrs1KO and DEN-treated control mice, as well as between the DEN-treated LIrs2KO and DEN-treated control mice." (PMID 28710407, 2017). "High CCND1 gene amplification is related to an aggressive tumor behavior and poor prognosis." (PMID 29140993, 2017). "In order to examine the functional significance of an increase in cyclin D1 expression in the tumor-associated fibroblasts, MDA-MB-231 cells were co-injected with hTERT fibroblasts expressing either cyclin D1 (cyclin D1Stroma) or control GFP vector (controlStroma)." (PMID 29137220, 2017). "However, our results indicate that the upregulation of TMPRSS2-ETV gene fusion by E2 enhances the tumor-promoting activities of the NF-κB pathway through induction of growth and metastasis-related genes (cyclin D1 and MMPs)." (PMID 28968951, 2017). "However, we observed a preferential accumulation of cyclin D1 in the cytosolic compartment in a subset of primary tumour samples and cell lines." (PMID 29066743, 2017).
tumor (continued). "A recent study proved that miR-195 had low expression rates in TSCC tumor samples, providing evidence that it might act as a tumor suppressor in this cancer type, by inhibiting Cyclin D1 and Bcl-2 expression." (PMID 29206174, 2017). "Signaling triggered by the CXCR4-CXCL12 binding and subsequent regulation of Cyclin D1 expression has been shown to regulate several biological functions in cancers, such as cell proliferation, tumor invasion and metastasis, angiogenesis, and cell–microenvironment interactions." (PMID 29020982, 2017). "However, in vivo, it promotes tumor progression by increasing the expression of Cyclin D1 and Cyclin E which aid in cell cycle progression." (PMID 29065514, 2017). "Furthermore the stromal cyclin D1 levels in the tumor were significantly greater than the adjacent normal stromal cyclin D1 in the same patients." (PMID 29137220, 2017). "IHC on representative BM biopsy specimen confirmed the presence of cyclin D1+/CD20+ tumour cells." (PMID 29066743, 2017). "Finally, we observed increased tumor necrosis and a lighter cyclin D1 staining with reduced staining areas." (PMID 28264020, 2017). "Similarly, MDM2-B (48 kDa), which is the most common MDM2 isoform observed in cancers, has exons 4–11 spliced out but is reported to promote tumor progression by inducing Cyclin D1 and Cyclin E in vivo." (PMID 29065514, 2017). "Western blotting and immunohistochemical assays revealed the upregulation of invasion-related proteins MMP2 and MMP9, and proliferation-related protein Cyclin D1 in the CEP55-overexpressing tumour tissues, which coincided with the aggressive phenotype displayed by Capan-1/CEP55 cells." (PMID 28724890, 2017). "CCND1 also dimerizes with cyclin-dependent kinases (CDK) 4/6 to regulate the G1-S phase transition and inhibits retinoblastoma protein (pRb) activity, and overexpression of CCND1 is associated with tumor progression in gastric and other cancers." (PMID 28427240, 2017). "Tumor growth, however, was slowed which might be due to the decrease in cyclin D1 expression and tumor cell proliferation." (PMID 29156681, 2017). "In addition, an increased expression of the proliferative marker Ki67, together with that of cyclin D1, cyclin E and cyclin A was found in tumor tissue sections obtained from G-1 treated mice with respect to those treated with vehicle." (PMID 29290975, 2017). "We thus evaluated CCND1 expression in the tumor tissues from ESCC patients." (PMID 28602785, 2017). "Consequently, this up-regulation was able to enhance the proliferation of ER-negative breast cancer cells in vitro via the GSK3β/β-catenin/cyclin D1 pathway and was able to promote tumor development in vivo." (PMID 29216929, 2017). "The inhibition of tumor cell growth may result from G0/G1-phase cell cycle arrest induced by a decrease in the expression of cyclin D1 and cyclin-dependent kinase 2 (CDK2) expression." (PMID 28383558, 2017). "Recent studies have shown that PRMT5 regulates tumor growth by modulating cyclin D1 expression." (PMID 28107179, 2017). "In Cp state, high DE miRNAs such as miRNA-449-A also showed interaction with the hub connectors CCND1 and TXNIP (encoding a thioredoxin-binding protein member of the alpha arrestin protein family that regulates redox signaling, and possibly a tumor suppressor)." (PMID 28824643, 2017). "This distinct cyclin D1 distribution seems to be specific of this tumor and may be of help in its recognition." (PMID 27158455, 2016). "As predicted, the logistic regression analysis using the pooled data confirmed that a high level of cyclin D1 expression, male sex, long tumor length, poor tumor cell differentiation, and advanced AJCC staging were independent factors that increased postoperative distant metastases." (PMID 27145270, 2016).
tumor (continued). "Previous studies showed EBV could encoded LMP1 to enhance the promoter activity of CCND1 in NPC, and miR-144 suppressed the expression of PTEN to increase the expression of CCND1 to promote tumor migration and invasion." (PMID 26795575, 2016). "Phosphorylation of the related signaling by berberine may be responsible for its various biological functions, and our finding shows Cyclin D1 phosphorylation by berberine may be related to Cyclin D1 degradation in tumor cells." (PMID 27854312, 2016). "Additionally, it appears that cyclin D1 and D3 can compensate for one another in driving tumor initiation and progression." (PMID 26857361, 2016). "Moreover, 143B-shRNA1 tumours displayed remarkably lower cyclin D1, pERK1/2 and TEM8 expression compared with the control group." (PMID 26996335, 2016). "Cyclin D1 silencing interfered with PCa oncogenic phenotype by inducing growth arrest in the G1 phase of cell cycle and reducing soft agar colony formation, migration, invasion in vitro and tumor formation and neo-angiogenesis in vivo." (PMID 26689991, 2016). "Cyclin D1 overexpression has been shown to correlate with early cancer onset and tumor progression." (PMID 27095572, 2016). "Significantly less cells were stainned positive by anti-cyclin D1 antibodies in the siRNA/collagen treated tumor cells, suggesting that cyclin D1 was significantly downregulated; while P21 expression was significantly increased, indicating that the cell cycle was inhibited." (PMID 27029190, 2016). "As a natural product with a long history and being intensively focused on its anti-tumor activity, berberine was reported to suppress Cyclin D1 expression in various human cancer cell lines, however, few of studies reported the underlying mechanism on Cyclin D1 inhibition action of berberine." (PMID 27854312, 2016). "The same result was obtained in tumour cells using an HA-tagged version of Ccnd1." (PMID 27181366, 2016). "Then, to test whether the forced association of Ccnd1 in the membrane could induce invasion of tumor cells, we have built a Ccnd1 with the same membrane-anchor motif of K-Ras fused at the C-terminus." (PMID 27105504, 2016). "Importantly, we observed a decrease in cyclin D1-positive cell numbers in tumour samples expressing higher levels of KIF3A." (PMID 27596264, 2016). "Immunostaining with cyclin D1 seems to be specific of this tumor subtype." (PMID 27158455, 2016). "Moreover, cotransfection with EGFR, AKT2, or CCND1 not only counterbalanced the tumor suppressor effects of miR-2861, but also promoted cancer cell growth and enhanced cell invasion ability." (PMID 27364926, 2016). "Then, we propose that cytoplasmic Ccnd1 could be indicative of tumor cells with a high invasive potential." (PMID 27105504, 2016). "Logistic regression analyses for the training cohort demonstrated that a high level of cyclin D1 expression, together with male sex, elderly age, poor tumor cell differentiation, and advanced AJCC stages, were independent factors that increased postoperative distant metastases." (PMID 27145270, 2016). "In addition, the existence of a Ccnd1·Cdk4-Pxn-Rac1 axis helps explain the invasive properties of tumours overexpressing Ccnd1." (PMID 27181366, 2016). "However, we did find that levels of the β-catenin target gene cyclin D1 were significantly augmented in normal epithelial and tumor cells upon VDR ablation." (PMID 27768599, 2016).
tumor (continued). "The RB pathway was considered disrupted in a tumor if one of the following events occurred: 1) RB1 mutation/homozygous deletion/underexpression; 2) CDKN2A mutation/homozygous deletion/underexpression; or 3) CCND1 overexpression." (PMID 27832204, 2016). "Overall, this result suggests that the presence of Ccnd1 in the cell membrane of tumor cells may be a marker of poor prognosis." (PMID 27105504, 2016). "To confirm that miR-1296 suppresses tumor cell growth due to CCND1 regulation, we found that CCND1 cDNA overexpression could rescue the growth suppression induced by miR-1296 overexpression alone." (PMID 26799586, 2016). "Furthermore, immunoblotting analysis showed that docetaxel treatment led to cell cycle arrest by decreasing cyclin D1 and c-myc and by increasing tumor suppression gene p27." (PMID 27487140, 2016). "However, this resistance was specifically reduced in cyclin D1-expressing cells after pomalidomide pre-treatment that modifies tumor cell/microenvironment interactions." (PMID 27286258, 2016). "AMPA decreases cyclin D1 to inhibit tumor cell proliferation and metastasis." (PMID 26840261, 2016). "However, our previous study also indicated that transactivation of cyclin D1 through the tyrosine-phosphatase activity of EYA1 is required for tumor growth and cellular proliferation." (PMID 27203207, 2016). "Due to decreased proliferation and lower activation of the STAT3-cyclin D1 axis in HepG2 cells following exposure to HCMV in tumor biopsies, we assessed whether HepG2 cells infected with HCMV have a reduced oncogenic potential." (PMID 27626063, 2016). "In addition, dysregulation of the G1 to S transition is one of the most important reasons for tumor formation, which is tightly linked to unregulated PCNA and Cyclin D1 expression." (PMID 27492854, 2016). "Interestingly, accumulating evidence shows that PA possesses anti-cancer property by targeting cyclin D1-regulated cell cycle of tumor cells." (PMID 27999546, 2016). "Moreover, our results also demonstrated miR-326/330-5p clusters exerted its tumor suppressive role on NPC through targeting cyclin D1." (PMID 27816050, 2016). "In this study, we found that CCND1 was upregulated in most of the tumor types." (PMID 26655252, 2016). "Additionally, studies have shown that the t(X;18) translocation influences tumor behavior partly through cyclin D1 activation." (PMID 27334220, 2016). "The multivariate Cox regression analysis confirmed that a low level of cyclin D1 expression, together with short tumor length, well tumor cell differentiation, and earlier AJCC staging, is an independent predictor favoring both OS and DMFS in the pooled cohort." (PMID 27145270, 2016). "The cyclin D1 was mainly stained in the nuclei of the tumor cells." (PMID 27145270, 2016). "Despite these limitations, 9 mature miRNAs exhibited significant and markedly reduced expression levels, including miR-204, a miRNA found particularly enriched in the proximal mouse epididymis and miR-138-5p, a potential tumor suppressor that inhibits cyclin D1 (Ccnd1) expression." (PMID 27695046, 2016). "Moreover, tumor cell-intrinsic RelB was responsible for the abundant levels of c-Myc, cyclin D1, Bcl-2 and Bcl-xL, which are key regulators of cell cycle transition, apoptosis and proliferation in EEC." (PMID 27711077, 2016). "In this work, we show that the Ccnd1·Cdk4 complex phosphorylates a subpopulation of Pxn present in membrane ruffles but not in FAs, which is functionally relevant in the control of cell spreading and invasion in both normal fibroblasts and tumour cells." (PMID 27181366, 2016).